PRKAR1A (protein kinase cAMP-dependent type I regulatory subunit alpha)
Diseases named in the same sentence as PRKAR1A in open-access papers (continued):
Sharing a sentence is not in itself a finding about the gene and the disease.
cancer (continued). "We first analyzed the frequency of PKA-activating somatic alterations in the TCGA Pan Cancer Atlas, including both PRKACA gain-of-function and PRKAR1A loss-of-function mutations in addition to copy number alterations across multiple cancers." (PMID 36692000, 2023). "We found that ECs harbored not only known mutations in driver genes, such as ARID1A, CTNNB1, PIK3CA, and PTEN, but also novel mutations in cancer-related genes, such as KMT2C and PRKAR1A." (PMID 35626111, 2022). "Mutations in cancer-related genes (KMT2C, NOTCH2, PRKAR1A, SDHA, and USP6) and genes related to EC (ARID1A, CTNNB1, PIK3CA, and PTEN) were identified with high frequencies among the three samples." (PMID 35626111, 2022). "Although a TCGA analysis identified MEN1 and PRKAR1A as putative cancer genes in ACC, the low frequency of mutations—4.7% and 2.3% for MEN1 and PRKAR1A, respectively—render their importance in this disease at best marginal." (PMID 33148256, 2020). "Other cancer-related genes, such as COL7A1, PRKAR1A, ERCC3, and MTAP, had variants with a conflicting interpretation of pathogenicity or VUS, or they were not reported in ClinVar." (PMID 32443704, 2020). "Additional cancer genes recurrently mutated in adenomyoepitheliomas included TERT (4/31, 13%, all hotspot promoter mutations) and PRKAR1A (2/31, 6%)." (PMID 29739933, 2018). "In previous studies, PRKAR1A has been reported to be overexpressed in a wide array of cancer types, and to be correlated with poor prognosis in cancer patients." (PMID 26203557, 2015). "Furthermore, the downregulation of PRKAR1A expression enhances the migration of cancer cells while suppressing that of CSCs." (PMID 38474121, 2024). "However, the cancer cell-killing effect decreased following PRKAR1A shRNA treatment; cytotoxicity against CSCs increased in a concentration-dependent manner." (PMID 38474121, 2024). "However, consistent with the results of proteomic analysis, PRKAR1A was commonly expressed in cancer cells and CSCs." (PMID 38474121, 2024). "Additionally, PRKAR1A demonstrated the capacity to influence the sensitivity of cancer cells and CSCs to anticancer agents, thereby impacting their cell-killing effects." (PMID 38474121, 2024). "Our subsequent assessment of the effect of PRKAR1A on cancer cells and CSCs focused on the key features of cancer growth and metastasis, including short-term cell proliferation and long-term colony formation, both of which are regulated by PRKAR1A in opposite directions in these cell types." (PMID 38474121, 2024). "Therefore, we evaluated the effect of PRKAR1A knockdown on the cytotoxic effects of anticancer drugs on drug-resistant cancer cells." (PMID 38474121, 2024). "In this regard, we generated drug-resistant cancer cell lines and CSCs to investigate whether decreased PRKAR1A levels can reduce chemoresistance in cells with inherent drug resistance." (PMID 38474121, 2024). "Targeting PRKAR1A could offer a strategic approach for overcoming the limitations of conventional cancer treatment and pave the way for new therapeutic approaches." (PMID 38474121, 2024). "Thus, the downregulation of PRKAR1A expression in cancer cells signifies the ERK phosphorylation-facilitated induction of EMT and increased stemness, elucidating the reasons behind the observed enhancements in cell proliferation and migration." (PMID 38474121, 2024). "However, further research is required to elucidate the effect of reduced PRKAR1A expression on cancer aggressiveness." (PMID 38474121, 2024). "Moreover, the lentivirus also encoded for cAMP-dependent protein kinase type I-alpha regulatory subunit (PRKAR1A), which is an overexpressed protein that promotes T-cell activation, and subsequently their capacity to kill cancer cells." (PMID 36980187, 2023).
cancer (continued). "Moreover, four cancer-associated genes showed a high frequency of copy number gain in both datasets (i.e. TERT, FCGR2B, CD79B and PRKAR1A)." (PMID 29371938, 2017). "While analyzing multiple cancer disorders, we found highly variable expression among genes implicated in cancer: EEF1A1, GNAS, NPM1, PIM1, and RHOA are known oncogenes; H3F3A, PTPRC, SMARCB1, and B2M are possible oncogenes; and CASP8, JAK1, and PRKAR1A are known tumor suppressor genes." (PMID 34174938, 2021). "The TCGA-identified putative cancer genes MEN1 and PRKAR1A were found in low frequency—4.7 and 2.3%, respectively." (PMID 33148256, 2020). "Of the ‘Cancer census genes’ most frequently involved in a copy number gain, four were in common with those in the TCGA-data (i.e. FCGR2B, TERT, CD79B and PRKAR1A)." (PMID 29371938, 2017). "Although PRKAR1A expression was not consistently high in the analyzed data of patients with cancer, it was highly expressed in patients with LIHC." (PMID 38474121, 2024). "Moreover, both sample sets shared four genes in their ‘top 20’ list of ‘Cancer census genes’ most frequently involved in a copy number gain (i.e. TERT, FCGR2B, CD79B and PRKAR1A)." (PMID 29371938, 2017).
genetic disorder (3 papers, 2015 to 2020). "As PRKAR1A haploinsufficiency in humans causes CNC, our study may provide novel mechanistic insights regarding the cardiac mortality associated with this hereditary genetic disorder." (PMID 32212257, 2020).
infection (3 papers, 2020 to 2022). The state of being infected such as from the introduction of a foreign agent such as serum, vaccine, antigenic substance or organism. "Notably, SOD1 is an important interaction molecule that exists both in BALF, PBMC and serum, and participates in early and late stages of infection, followed by PRKAR1A, IARS, SNRNP200, and DHX15." (PMID 34952961, 2021). "On the contrary, MOPV infection led to the late (48 h) release of PSMD2, RPS11, HNRNPA3, ATP1A1, TARS1, and PRKAR1A, whereas significantly elevated levels of IGFBP3 were found at both timepoints." (PMID 35337059, 2022).
adenocarcinoma (1 paper, 2016). A common cancer characterized by the presence of malignant glandular cells. "Decreased mRNA and protein levels of PRKAR1A were observed in adenocarcinoma tissues, thereby instigating an in vitro experiment to assess if PRKAR1A was required for E-cadherin expression." (PMID 27995993, 2016).
cardiovascular disease (1 paper, 2021). "Overall, 86 genes were identified to significantly modify the cardiovascular disease severity in PXE, of which four genes are present in both tests (HCAR3, CNGB3, SI, and PRKAR1A)." (PMID 34169069, 2021). "For PRKAR1A, SI and CNGB3 no relevant associations with cardiovascular disease were identified, except for a relatively weak association between CNGB3 and varicosity." (PMID 34169069, 2021).
hematologic malignancies (1 paper, 2015). "We studied Prkar2a- haploinsufficient (Prkar2a+/−), Prkar2b- haploinsufficient (Prkar2b+/−), Prkar2a−/− KO, as well as double-heterozygote (Prkar1a+/−x Prkar2a+/-) F1 mice for the development of hematologic malignancies." (PMID 26608815, 2015). "Cohorts of Prkar1a+/−, Prkar2a+/−, Prkar2a−/−, Prkar2b+/− and wild type (WT) mice have been observed between 5 and 25 months of age for the development of hematologic malignancies." (PMID 26608815, 2015).
hematopoietic tumors (1 paper, 2015). "Prkar2a-deficienct mice developed hematopoietic tumors with higher frequency than Prkar1a-deficient and WT mice." (PMID 26608815, 2015).
metabolic disorder (1 paper, 2021). "Consistent with the clinical observation that subjects with PDC tend to develop a metabolic disorder, series-clustering analysis detected several key lipid metabolic genes (PRKAR1A, ACSL4, SMPD3, etc.)." (PMID 34926685, 2021).
PRKAR1A also shares sentences with these, for which no sentence is quoted: pituitary adenoma (5 papers); melanotic schwannoma (3); acute myocardial infarction (2); blue nevus (2); brachydactyly (2); brachydactyly mental retardation syndrome (2); glioblastoma (2); McCune-Albright syndrome (2); van der Woude syndrome (2); Adrenal insufficiency (1); Albright hereditary osteodystrophy (1); Andersen/Andersen-Tawil syndrome (1); ankylosis (1); Anorexia (1); asthenozoospermia (1); attention deficit-hyperactivity disorder (1); autosomal dominant disease (1); Azoospermia (1); Beckwith-Wiedemann syndrome (1); benign tumors (1); bipolar disorder (1); bladder cancer (1); brain disease (1); breast ductal adenoma (1); breast tumors (1); cardiomyopathies (1); Carney complex, type 1 (1); cholangiocarcinoma (1); chondrodysplasia (1); chordoma (1).
A further 53 diseases each share a sentence with PRKAR1A in 1 paper.